GADD45A (growth arrest and DNA damage inducible alpha)
Diseases named in the same sentence as GADD45A in open-access papers (continued):
Sharing a sentence is not in itself a finding about the gene and the disease.
epilepsy (1 paper, 2024). A brain disorder characterized by episodes of abnormally increased neuronal discharge resulting in transient episodes of sensory or motor neurological dysfunction, or psychic dysfunction. "The results of this study highlight PTPRO and GADD45A as potential genes for the diagnosis and treatment of epilepsy." (PMID 38212777, 2024). "To explore the potential role of PTPRO and GADD45A in epilepsy treatment, we first conducted an interaction analysis between the proteins encoded by PTPRO and GADD45A and the targets of approved antiepileptic drugs." (PMID 38212777, 2024). "In summary, our findings underscore the potential of PTPRO and GADD45A as promising targets for the diagnosis and treatment of epilepsy." (PMID 38212777, 2024). "While our study integrated data from gene expression, gene co-expression, eQTL, PPI network, and drug–gene interaction to uncover the role of PTPRO and GADD45A in epilepsy diagnosis and therapy, there are still some limitations." (PMID 38212777, 2024). "Second, additional functional characterization would help to better understand the mechanisms of PTPRO and GADD45A in the pathogenesis and treatment of epilepsy." (PMID 38212777, 2024). "Our eQTL analysis revealed that several noncoding SNPs associated with epilepsy risk alter the expression of PTPRO and GADD45A in brain tissue." (PMID 38212777, 2024). "Therefore, the results of the PPI networks and drug–gene interaction further underscore the significant role of GADD45A in epilepsy therapy." (PMID 38212777, 2024). "Further analysis revealed that two of these DEGs, PTPRO and GADD45A, had not been previously reported to be associated with epilepsy." (PMID 38212777, 2024). "Expression quantitative trait loci analysis suggested that epilepsy risk single-nucleotide polymorphisms could be responsible for the altered PTPRO and GADD45A expression in human brain tissue." (PMID 38212777, 2024). "Therefore, we hypothesize that these SNPs may contribute to epilepsy risk by regulating PTPRO and GADD45A expression in human brain tissue." (PMID 38212777, 2024). "Our results suggest that GADD45A might serve as a potential therapeutic target for epilepsy." (PMID 38212777, 2024). "In this comprehensive analysis of epilepsy, we identified two new potential genes, PTPRO and GADD45A, and highlighted their crucial roles in epilepsy." (PMID 38212777, 2024).
Hepatomegaly (1 paper, 2017). Abnormally increased size of the liver. "Additionally, Gadd45a−/−/BCR-ABL recipients exhibited massive splenomegaly and hepatomegaly compared to WT/BCR-ABL recipients due to increased extramedullary hematopoiesis." (PMID 28086219, 2017).
HIV-1 infection (1 paper, 2011). The type species of lentivirus and the etiologic agent of acquired immunodeficiency syndrome (AIDS). "Andersen and coworkers have reported that the expression of GADD45A was increased following stressful growth arrest conditions as a result of HIV-1 infection." (PMID 21226936, 2011).
hypertrophic cardiomyopathy (1 paper, 2025). A condition in which the myocardium is hypertrophied without an obvious cause. "This was not surprising, since GADD45A has been shown to induce muscle atrophy, and a recent in silico study had already pointed to GADD45A as a hub protein underlying hypertrophic cardiomyopathy in humans." (PMID 40301189, 2025).
Hypoglycemia (1 paper, 2025). A decreased concentration of glucose in the blood. "Despite hypoglycemia, Gadd45a suppression in KO mice resulted in improved glucose tolerance compared to WT mice." (PMID 40301189, 2025). "Under hypoglycemia conditions, as observed in Gadd45a KO mice, insulin secretion by pancreatic β cells is increased." (PMID 40301189, 2025). "Our data demonstrate that Gadd45a suppression triggered systemic metabolic changes, including plasma hypoglycemia and diminished hepatic gluconeogenesis, which may undoubtedly affect the heart." (PMID 40301189, 2025).
infectious mononucleosis (1 paper, 2021). A condition characterized by an increase in mononuclear white blood cells and swollen lymph nodes, which is usually caused by infection with the Epstein-Barr virus. "Moreover, HLA-DMB, GADD45A, and ISG15 are reported to be involved in Epstein–Barr virus infection, one of the most common human viruses in the world, causing infectious mononucleosis and other illnesses." (PMID 34442377, 2021).
Insulin resistance (1 paper, 2023). Increased resistance towards insulin, that is, diminished effectiveness of insulin in reducing blood glucose levels. "Notably, Gadd45a-/- mice maintained better glucose tolerance and lower insulin resistance after HFD feeding." (PMID 37807064, 2023).
ischemic stroke (1 paper, 2025). A stroke disorder caused by obstruction of blood flow to the brain, due to thrombotic (local blood clot formation) or embolic (due to a blood clot or other material traveling from another site) event. "Leveraging multiple bioinformatic approaches, we pinpointed a critical gene signature within the ERK pathway—termed GSERK—that prominently included GADD45A, DUSP1, and GADD45B as central modulators implicated in ischemic stroke pathogenesis." (PMID 40636523, 2025). "The ROC curve analysis in the total sample set revealed moderate discriminatory capacity for DUSP1 (AUC = 0.75), GADD45A (AUC = 0.72), and GADD45B (AUC = 0.70), suggesting these genes may serve as potential diagnostic biomarkers for ischemic stroke." (PMID 40636523, 2025). "Our integration of multiple complementary machine-learning methods, like Boruta, SVM, LASSO, and random forest, provided rigorous confirmation of GADD45A, DUSP1, and GADD45B as robust biomarkers for ischemic stroke, substantially minimizing the risk of false discoveries inherent in genomic analyses." (PMID 40636523, 2025). "Using this approach, we identified a distinct gene signature—termed GSERK—including GADD45A, DUSP1, EREG, IL1B, JUN, and GADD45B as central regulatory nodes within ischemic stroke-related co-expression networks." (PMID 40636523, 2025). "Collectively, these results support the potential of DUSP1, GADD45A, and GADD45B as useful biomarkers for ischemic stroke, warranting further clinical validation." (PMID 40636523, 2025).
latent infection (1 paper, 2016). "The upregulation of transcripts of BBC3, GADD45A, MDM2, TP53I3, and downregulation of HEXIM1 during latent infection was confirmed as significant by RT-qPCR." (PMID 27898737, 2016).
lipid metabolic disorder (1 paper, 2022). "Additionally, three genes associated with lipid metabolism (Angptl8, Gadd45a, and Mid1ip1) are significantly downregulated in CD19−/− mice, providing further support for our argument that CD19−/− mice develop a lipid metabolic disorder." (PMID 35082296, 2022).
liver cirrhosis (1 paper, 2023). "In the same manner, the C allele at rs532446 of GADD45A was more common in CHB carriers with both raised ALT concentrations and liver cirrhosis." (PMID 37059745, 2023).
meningioma (1 paper, 2014). A generally slow growing tumor attached to the dura mater. "The GADD45A was once thought to be a potential genetic target for meningioma and other tumor pathogenesis; however, no genetic abnormalities were found in meningioma cell lines." (PMID 25485306, 2014).
muscle atrophy (1 paper, 2023). The loss of muscle tissue due to inactivity or disease. "However, it remained unknown whether GADD45A had similar effects on other skeletal muscles and whether GADD45A is sufficient to generate functional deficits that are characteristic of muscle atrophy." (PMID 37815864, 2023). "Interestingly, GADD45A also induces a third cellular change that is often observed in skeletal muscle atrophy: a striking dissociation between actual oxidative capacity and expression of MyHC isoforms that, in healthy skeletal muscle, are characteristic of oxidative muscle fibers." (PMID 37815864, 2023). "And yet, studies have also shown that gastrocnemius and soleus muscles of Gadd45a-knockout mice are not resistant to denervation-induced skeletal muscle atrophy." (PMID 37815864, 2023). "Another limitation of the current study is that it demonstrates that GADD45A expression in muscle fibers is sufficient to induce several cellular and phenotypic changes that are characteristic of muscle atrophy, but it does not determine whether GADD45A is necessary for these effects." (PMID 37815864, 2023).
myeloid leukemia (1 paper, 2023). A clonal proliferation of myeloid cells and their precursors in the bone marrow, peripheral blood, and spleen. "A dose-rate-dependent induction of CDKN1A and GADD45A genes and other apoptosis-related genes occurs following low dose exposure in the human myeloid leukemia ML-1 cell line." (PMID 38162630, 2023).
progeria (1 paper, 2019). "Indeed, impaired DNA demethylation in Gadd45a/Ing1 double-knockout mice has been shown to lead to a segmental progeria phenotype." (PMID 31156709, 2019).
rectal cancer (1 paper, 2024). A primary or metastatic malignant neoplasm that affects the rectum.
Skeletal muscle atrophy (1 paper, 2023). The presence of skeletal muscular atrophy (which is also known as amyotrophy). "Thus, GADD45A has a capacity to dissociate mitochondrial function from oxidative MyHC expression, a paradoxical phenomenon that is often observed in natural forms of skeletal muscle atrophy that are associated with increased GADD45A expression." (PMID 37815864, 2023).
skin squamous cell carcinoma (1 paper, 2021). A carcinoma arising from the squamous cells of the epidermis. "Recently, it has been reported that GADD45a silencing promotes cell proliferation and inhibits apoptosis in skin squamous cell carcinoma." (PMID 34272424, 2021).
squamous cell carcinoma (1 paper, 2021). A carcinoma arising from squamous epithelial cells. "In squamous cell carcinoma cells, knockdown of GADD45A inhibits apoptosis, with the reduction of BAX gene expression and induction of BCL-2 gene expression." (PMID 33406670, 2021).
testicular germ cell tumor (1 paper, 2023). A germ cell tumor arising from the testis. "Manku and Culty investigated the effects of inadequate gonocyte differentiation and formation of testicular germ cell tumor (TGCT), reporting that differentiating gonocytes and spermatogonia had upregulated pro-apoptotic genes Gadd45a and Cycs compared to non-differentiating gonocytes." (PMID 36793282, 2023).
thyroid cancer (1 paper, 2017). "In thyroid cancer cells, a chemopreventive non-steroidal anti-inflammatory drug, sulindac sulfide, blocks the PI3K-AKT pathway and leads to the activation of FOXO3, which increases the expression of Bim, GADD45A and p27KIP1 to promote cell cycle arrest and apoptosis." (PMID 29299162, 2017).
ulcerative colitis (1 paper, 2025). An inflammatory bowel disease involving the mucosal surface of the large intestine and rectum. "In colonic samples of both healthy individuals and those afflicted with ulcerative colitis (UC), we found that GADD45A was significantly decreased in patients with UC." (PMID 40236773, 2025). "In addition, we identified GADD45A as a novel regulator involved in intestinal barrier integrity and the development of ulcerative colitis." (PMID 40236773, 2025).
tumor (145 papers, 2002 to 2026). "Comparing the expression of the CDDP-DTP-associated genes between tumor and normal adjacent tissue, and its clinical relevance, we found that six (GADD45A, SOCS1, EPS15, GLI3, NR2F2, and RCOR1) of the hub genes have significant differences." (PMID 37916165, 2023). "In oral squamous cell carcinoma (OSCC), low GADD45A expression is associated with poorer OS and predicts lower tumor cell differentiation, higher lymphatic metastasis rates, and increased cancer recurrence." (PMID 37256211, 2023). "Gadd45a-deficient mice are more prone to tumor cell formation induced by DNA damage, and also show loss of genomic instability, oncogene transformation, centrosome amplification and cell senescence functions." (PMID 37828502, 2023). "Among the DEGs that fell into this group, there were tumor-associated genes such as GADD45A, PPM1D, PLK2 and CREBRF." (PMID 35682850, 2022). "GADD45A expression is elevated in several cancer cells after treatment with anti-tumor drugs and is positively associated with drug efficiency." (PMID 35281859, 2022). "Given the important role of GADD45A in modulating cell responses to DNA damage and association with tumor prognosis, GADD45A is probably involved in ADMA-mediated signaling pathways in tumor cells." (PMID 27180883, 2016). "In details, the in vivo constitutive activation of Erk-1, JNK, Gadd45a and Caspase8 was evaluated in high-risk haemathological neoplasms." (PMID 19298651, 2009). "The down-regulation of Gadd45a and Pmaip1 indicated that in addition to affecting the cell cycle, conotoxin may also cause DNA damage and induce tumor cell formation, leading to cell canceration." (PMID 37828502, 2023). "Notably, this set contained several activated DEGs from sets of those found with cells producing uS10mut1, uS10mut2, or uS10mut3, including tumor-associated genes such as GADD45A, PPM1D, MDM2, and CREBRF." (PMID 35682850, 2022). "Additionally, it is shown that Gadd45a tumor suppressive function is associated with modulation of AKT, p38 and Stat5 signaling pathways, leading to deregulated cellular proliferation and apoptosis." (PMID 28086219, 2017). "Here, we test the hypothesis that specific candidate gene methylation markers (CCNA1, NDN, CD1A, DCC, p16, GADD45A) are associated with tumor recurrence and survival, in a well-characterized, prospective, cohort of 346 HNSCC patients." (PMID 26518708, 2015). "Growth arrest and DNA damage-inducing protein 45 (Gadd45) family members, including Gadd45a, Gadd45b, and Gadd45g, have been implicated in many basic processes, such as DNA repair, genome stability, epigenetic regulation, cell cycle arrest, apoptosis, tumor development, and embryogenesis." (PMID 34601500, 2021). "Aside its well-established pro-apoptotic and tumor suppressor activity, a pro-survival role has also been reported for GADD45A in some studies." (PMID 40301189, 2025). "The study elucidated that LDVs anti-tumor mechanism operates through the generation of ROS, which in turn upregulates GADD45A." (PMID 40648712, 2025). "GADD45A itself is regarded as a tumor suppressor capable of delaying, or even preventing, tumor development through the regulation of cell cycle, DNA repair, and apoptosis." (PMID 40301189, 2025). "Our study uncovered the crucial tumor-suppressive role of METTL1-mediated tRNA m7G modification in BC by promoting the translation of GADD45A and RB1 mRNAs, selectively blocking the G2/M phase of the cell cycle." (PMID 38822363, 2024).
tumor (continued). "Among these, GADD45A serves as a tumor suppressor in several cancers and regulates cell cycle arrest, cell survival, and apoptosis in response to physiological and environmental stress." (PMID 38822363, 2024). "GADD45A gene plays a essential roles in regulation of many cellular functions including DNA repair, cell cycle arrest control, pro-apoptotic activity and tumor growth suppression." (PMID 37658091, 2023). "Only the expression of GADD45A was significantly increased in tumor samples (p < 0.05) compared to normal tissue, which is in line with the overexpression we found in CDDP-DTP cells." (PMID 37916165, 2023). "As a member of the growth arrest and DNA damage gene (Gadd) family, Gadd45a was previously reported to be closely related to the prognosis of tumor patients and was found to be a cell cycle regulator." (PMID 36821012, 2023). "GADD45A proteins serve as tumor suppressors in various cancers and are connected to multiple cell signaling molecules; defects in the GADD45A protein are closely associated with the pathogenesis of malignancy 26,27." (PMID 35281859, 2022). "A previous study has shown that TARID activated TCF21 expression by interacting with both the TCF21 promoter and GADD45A during tumor development." (PMID 36401313, 2022). "The diaphragm demonstrated similar results, such that MURF1, atrogin, and Gadd45a were all significantly increased at 4 weeks of tumor bearing." (PMID 36346680, 2022). "GADD45A is associated with DNA damage and is proapoptotic, and ATM, as a tumor suppressor gene, plays a role in the initiation and/or progression of MCL." (PMID 34174847, 2021). "A previous study described GADD45A as a tumor suppressor capable of inducing G2/M phase arrest and apoptosis." (PMID 33221751, 2020). "There wasalso a decrease in DNA methylation of the GADD45A in HepG2 cells inco-culture, evidencing that BjussuLAAO-II is able to alter the methylation patternof this gene even in the tumor microenvironment." (PMID 31131003, 2019). "The Gadd45a gene is inactivated by promoter DNA methylation in various types of cancer and tumor cell lines." (PMID 29966255, 2018). "With regards to their functions, CHEK1, RAD51 and CDC25A have been suggested to promote tumor development, while GADD45A can act as a tumor suppressor." (PMID 30042885, 2018). "The present study indicates that loss of Gadd45b, like Gadd45a, accelerated CML, behaving as a tumor suppressor, albeit by a different mechanism than Gadd45a." (PMID 30279966, 2018). "Our data provides an important extension of this notion, showing for the first time that Gadd45a is a tumor suppressor in BCR-ABL driven leukemogenesis." (PMID 28086219, 2017). "In the pathway in cell cycle, we found that the expression of Ccna2, Cdc25a, Mcm3, Mcm6, Ccnb2, Mcm5, Cdk1, Gadd45a were down-regulated in the MMQ tumor stem-like cells." (PMID 28163656, 2017). "BLI showed increasing radiance values corresponding to increasing tumor growth higher in GADD45A-siRNA tumors compared with control, while pcDNA3.1-GADD45A showed a lower radiance than control." (PMID 28445981, 2017). "The current study highlights a unique role for Gadd45a as a tumor suppressor in BCR-ABL driven leukemogenesis, characterized by its’ loss causing an increase in the number and self-renewal capability of CML cells." (PMID 28086219, 2017).